FHIT (fragile histidine triad diadenosine triphosphatase)
Diseases named in the same sentence as FHIT in open-access papers (continued):
Sharing a sentence is not in itself a finding about the gene and the disease.
lung carcinoma (continued). "Regular expression of the FHIT helps inhibit the development and progression of human lung cancer by activating the miR-30c-targeted metastatic genes Metadherin, high-migration group AT-hook 2, vimentin, and fibronectin, helping inhibit EMT and cancer cell metastasis." (PMID 36831487, 2023). "Interestingly, FHIT was shown to inhibit AKT activation leading to one mechanism by which FHIT decreases lung cancer cell survival." (PMID 33800889, 2021). "FHIT has been shown to have considerable relevance in lung cancer." (PMID 32318107, 2020). "Interestingly, all the three significant epistasis—-RGL1:RAD51B in ALL and NSCLC lung cancer, SYNE1:RNF43 in ADE and FHIT:TSPAN8 in SQC risk development—-were displayed as interaction between networks." (PMID 30956756, 2019). "The odd ratio (OR) for FHIT methylation in cancer group was 3.43 (95% CI: 1.85 - 6.36) in random effects model, and 2.03 (95% CI: 1.60 - 2.57) in fixed effects model, indicating a slight increase of methylation in lung cancer tissues." (PMID 28036263, 2017). "Lung cancer cell clones carrying conditional FHIT transgenes showed significant suppression of xenograft tumor growth, suggesting that treatments to restore endogenous FHIT expression in lung cancers would result in decreased tumorigenicity." (PMID 26796853, 2016). "Taken together, these results show that FHIT inhibits metastasis of human lung cancer cell lines." (PMID 25340791, 2014). "Also, the expression of FHIT and miR-30c was positively correlated in primary lung cancer tumors (n = 20, coefficient = 0.851 and P<0.0001)." (PMID 25340791, 2014). "According to the study results, the enforced expression of miR-29s in lung cancer cell lines results in a global reduction of DNA methylation, thus leading to re-expression of methylation-silenced tumor suppressor genes (FHIT, WWOX) and, additionally, inhibits tumorigenicity in vitro and in vivo." (PMID 23086271, 2013). "However, the precise role of FHIT loss in lung cancer carcinogenesis and tumor development is not fully understood." (PMID 39762409, 2025). "Moreover, Semba also found FHIT could regulate the expression of survivin via PI3K/Akt pathway in lung cancer." (PMID 24757411, 2014). "Finally, to determine if our experimental findings could be relevant to the pathogenesis of human lung cancer, we examined the expression pattern of FHIT, miR-30c, MTDH and HMGA2 in primary tumor tissues and matched lymph node metastatic tissues." (PMID 25340791, 2014). "For many tumors, abnormal FHIT gene regulatory transcription and FHIT protein deletion or re-education have been identified in a great variety of human tumors and tumor cell lines, such as lung cancer, breast cancer, cervical carcinoma, ovarian cancer, and so on." (PMID 18366613, 2008). "We further showed that FHIT inactivation leads to the activation of DNA damage repair pathways, including the HRR and NHEJ pathways, in lung cancer cells." (PMID 39762409, 2025). "Duan et al11 used the biological processes (BP) neural network to establish an auxiliary diagnosis model of lung cancer with genes of P16, RASSF1A, and FHIT, and the AUC of this model was 0.76." (PMID 37051625, 2023). "The FHIT gene is one of the most well-known genes at this common fragile site and has been reported to undergo LOH in >76% of lung cancer." (PMID 33450833, 2021). "FHIT-mimetic peptide (7–13, QHLIKPS) has been reported to interact with ANXA4 restoring chemosensitivity to paclitaxel in lung cancer cells." (PMID 34901149, 2021).
lung carcinoma (continued). "The methylation frequencies of 6 genes (FHIT, p16, MGMT, RASSF1A, APC, DAPK) in lung cancer patients, the basic clinical information, and tumor marker levels of these patients were analyzed." (PMID 34257703, 2021). "This study identified FHIT, MGMT, P16, RASSF1A, APC, and DAPK as methylation markers of lung cancer through literature review and previous studies." (PMID 34257703, 2021). "The FHIT gene encompasses the common fragile site FRA3B on chromosome 3 and shows a high rate of LOH in lung cancer, particularly in smokers." (PMID 32604993, 2020). "Expression of FHIT and miR-30c has been shown to be inversely correlated with HMGA2 expression in lung cancer and squamous cell carcinoma of the vulva." (PMID 31217897, 2019). "In conclusion, despite these limitations, our meta-analysis advocates that methylated SOX17, CDO1, ZFP42, TAC1, FAM19A4, FHIT, MGMT, p16, and RASSF1A are useful biomarkers in the screening and auxiliary detection of lung cancer." (PMID 28644424, 2017). "FHIT suppressed the metastasis of lung cancer by inhibiting micro-RNA-mediated EMT, and KY-05009 and TNIK inhibited the invasion of human lung cancer cells by down-regulating TGF-β1-mediated EMT." (PMID 26636541, 2016). "Such previous studies identified the RASSF1A, PITX2, SHOX2, TFPI-2, FHIT, p16, CDH13, and APC genes as predictors of recurrence of lung cancers." (PMID 23544068, 2013). "FHIT LOH was increased in advanced disease and in poorly differentiated tumours, supporting the significance of FHIT inactivation in lung cancer development." (PMID 12771912, 2003). "FHIT wild-type lung cancer cell lines, including HCC827 and H1650, were used to generate FHIT-KO clones, and FHIT-null cell lines, including H1299 and H460, were used to generate FHIT-OE clones." (PMID 39762409, 2025). "We first verified the interaction between FHIT and HSP90 in HCC827 and H1299 lung cancer cells." (PMID 39762409, 2025). "In addition, FHIT impedes tumor invasion and metastasis through its ability to suppress epithelial-mesenchymal transition (EMT) in lung cancer cells." (PMID 36544755, 2022). "Numerous studies showed that in lung cancer, the hypermethylation modification of the CpG island in promoter regions of tumor suppressor genes, such as FHIT, p16, MGMT, RASSF1A, APC, and DAPK, leads to the occurrence of lung cancer and poor prognosis in lung cancer patients." (PMID 34257703, 2021). "MiR-29 family reverts abnormal methylation in lung cancer by targeting DNA methyltransferases 3A and 3B (DNMT3A and DNMT3B), induces re-expression of methylation-silenced tumor suppressor genes, such as FHIT and WWOX, and inhibits tumorigenicity in vitro and in vivo." (PMID 34299277, 2021). "Therefore, we advocate that methylated SOX17, CDO1, ZFP42, TAC1, FAM19A4, FHIT, MGMT, p16, and RASSF1A are useful in the screening and auxiliary detection of lung cancer." (PMID 28644424, 2017). "In addition, the methylation of FAM19A4, FHIT, and MGMT were reported to play important roles in the occurrence and deterioration of lung cancer." (PMID 28644424, 2017). "Three regions: 3p14.2 (deletion), 9p21.2q21.31 (amplification), and 20q13.12 (amplification) were commonly found in HN4 and HN31 as the same cluster in our analysis, and five genes (FHIT, MMP9, GNA14, GNAQ, and PSAT1) were involved in tumorigenesis in lung cancer and colon cancer." (PMID 27501229, 2016).
lung carcinoma (continued). "The results revealed that both wild-type and hydrolase-dead mutant FHIT successfully reduced the BRCA1 and RAD51 protein levels in FHIT−/− lung cancer cells, suggesting that the Ap3A hydrolase activity of FHIT is not crucial for HRR protein stability or DNA damage repair signaling." (PMID 39762409, 2025). "Additionally, FHIT deletions (Fragile Histidine Triad Diadenosine Triphosphatase) or hypermethylation are observed in from 40% to 70% of NSCLC cases and from 50% to 80% of SCLC cases, underscoring their significance in lung cancer progression." (PMID 38001653, 2023). "In locally advanced lung cancer, FHIT mRNA expression is frequently absent via the CpG methylation." (PMID 36831487, 2023). "Deletions in HYAL2 and FHIT, present in lung tumors, have been shown to be significantly concordant with deletions in paired sputum samples and significantly higher in patients with lung cancer compared to smokers without lung cancer." (PMID 24840047, 2014). "Finally, we demonstrate that the expression pattern of FHIT and miR-30c is inversely correlated with that of MTDH and HMGA2 in normal tissue, non-metastatic and metastatic tumors, serving as a potential biomarker for metastasis in lung cancer." (PMID 25340791, 2014). "Interestingly, several studies have revealed that a significantly higher level of FHIT LOH occurs in lung cancers from smokers compared with that from nonsmokers, indicating that this could be a predictive marker of an early event in the genesis of smoking-related cancers." (PMID 33450833, 2021). "The most frequently analyzed genes like p16, DAPK, APC, RASSF1A, MGMT, FHIT, RARß and GSTP1 were applied as a means of detecting lung cancer or as prognostic factor but none of them had been used for therapy monitoring." (PMID 25675432, 2015). "Next, we were interested in identifying the expression patterns of FHIT, miR-30c, MTDH and HMGA2 in lung cancer progression and examined their mRNA levels in normal, non-metastatic and metastatic lung tissues." (PMID 25340791, 2014). "While CDKN2A, DAPK1 and APC are found hypermethylated both in smoking and non-smoking lung cancer patients others, like APC, FHIT, RASSF1A or CCND2 are strictly correlated with smoking." (PMID 23086271, 2013). "To further investigate the role of FHIT in the metastatic progression of lung cancer, we generated luciferase-tagged human A549 and H1299 non-small-cell lung cancer (NSCLC) cell lines with enforced stable expression of FHIT, and confirmed overexpression of protein by immunoblotting." (PMID 25340791, 2014). "A study conducted among HPV infected, nonsmoking, female lung cancer patients from Taiwan suggested that tumorigenesis may be in part due to the increase in frequency of the FHIT LOH, reducing the expression of FHIT." (PMID 22363346, 2012).
breast carcinoma (29 papers, 2003 to 2025). "FHIT expression is reduced in many breast cancers, and its nuclear translocation promotes breast cancer cell proliferation; moreover, loss of FHIT expression or function were correlated with patient poor prognosis and advanced stage." (PMID 34368151, 2021). "Previous studies have shown that FHIT expression levels are significantly increased in a number of DNA repair-deficiency tumours, such as breast cancer and colorectal cancer." (PMID 25436004, 2015). "Analysis of FHIT gene in a series of human primary breast cancer revealed an allelic loss in 25% and abnormal transcripts in approximately 30% of the cases." (PMID 22295218, 2011). "Silencing of the FHIT gene by promoter hypermethylation occurs in breast carcinomas, especially those with the significant amount of mutations in its genomic structure." (PMID 22295218, 2011). "Recently, we have reported loss of heterozygosity (LOH) in FHIT gene locus and its flanking region on chromosome 3p in Egyptian breast cancer patients." (PMID 22295218, 2011). "Underexpression of the FHIT gene has frequently been linked to human cancer including breast cancer." (PMID 17164758, 2007). "Loss of BRCA1 is associated with a more aggressive phenotype in sporadic breast cancer and concomitant loss of FHIT and BRCA1 alleles has also been reported in a number of repair-deficient cancers including breast cancer and ovarian cancers." (PMID 17164758, 2007). "Recently, it was reported that alterations in the FHIT locus detected by DNA and/or reverse transcription–PCR analysis correlated with a loss of Fhit protein expression in lung, cervical, and breast carcinomas." (PMID 12865924, 2003). "Interestingly, FHIT gene has been associated translocation in cancer while the LEPREL1 gene has also been associated with breast cancer development." (PMID 32714374, 2020). "The top SNV here is present in the intron of FHIT, a tumor suppressor involved in apoptosis and prevention of the epithelial-mesenchymal transition, and one of the earliest and most frequently altered genes in most human cancers, including predisposition in breast cancer." (PMID 33793571, 2021). "Restoration of FHIT expression induced apoptosis and suppressed tumorigenicity in lung, cervical and breast cancer models, suggesting that FHIT is a bona fide tumor suppressor." (PMID 39762409, 2025). "This indicates that the repression mechanism of LINC00173 on FHIT is conserved between lung and breast cancer." (PMID 38069335, 2023). "The results of that study showed that mutations in the FHIT gene were significantly associated with hypermethylation of the promoter region, resulting in complete inactivation of the FHIT gene and leading to breast cancer development." (PMID 37372369, 2023). "Double allelic inactivation of the FHIT gene and its complete silencing of the FHIT gene by heterozygous deletion has also been found in breast cancer." (PMID 36831487, 2023). "Recently, detection of FHIT methylation identified by meta-analyses was shown to be useful for the early diagnosis of breast carcinoma and NSCLC." (PMID 32375395, 2020). "3p would include TGFBR2, CNTN4, and CHL1 (reported for colorectal cancer) and CNTN6 (for breast cancer), as well as FHIT, ROBO1-GRE1 and SETMAR-LRRN1." (PMID 26247464, 2015). "The present findings highlight the FHIT gene as an interesting target for extensive analysis in Egyptian breast cancer patients." (PMID 22295218, 2011). "The significant association of FHIT mutation and hypermethylation leads to the complete inactivation of FHIT gene in patients with breast cancer." (PMID 22295218, 2011). "From these data, we conclude that homozygous deletion or HD of FHIT gene exons occurs at high frequency in Egyptian breast cancer patients." (PMID 22295218, 2011). "Fragile histidine triad (FHIT) gene located at chromosome 3p14.2 is a putative tumour suppressor gene involved in the pathogenesis of breast cancer." (PMID 22295218, 2011).
breast carcinoma (continued). "In this study, we investigated the pattern of homozygous deletion that target the FHIT gene exons 3 to 9 genomic structure in Egyptian breast cancer patients." (PMID 22295218, 2011). "In the present study, we aimed to investigate the frequency of exon deletions that affect the FHIT gene in a series of primary breast cancer tumours in Egyptian population." (PMID 22295218, 2011). "FHIT gene methylation was also reported in serum of sporadic breast cancer in a CpG island methylator phenotype (CIMP) screening." (PMID 22295218, 2011). "FHIT homozygous deletions in samples with 3p14.2 aberrations were also found in the benign breast lesions of two women with familial tendency to breast cancer." (PMID 22295218, 2011). "Here we aimed to understand the genetic alterations that affect FHIT gene in an Egyptian population of primary breast cancer patients." (PMID 22295218, 2011). "The presence of homozygous deletion of FHIT exons in breast cancer samples implicates that alteration in FHIT gene is an important event in breast pathogenenesis in this population." (PMID 22295218, 2011). "FHIT exons deletion in breast cancer samples were compared with patients' clinicopathological parameters including tumour type, tumour grade, patient's age at diagnosis, and lymph node status." (PMID 22295218, 2011). "Here, we found that 65% of the breast cancer patients investigated showed homozygous deletions (HDs) in at least one FHIT exon (40 out of 62)." (PMID 22295218, 2011). "Overall, we show here that FHIT genomic structure is subjected to extensive allelic alterations represented by exon homozygous deletion in a series of Egyptian primary breast cancer." (PMID 22295218, 2011). "Univariate analysis of disease-free survival showed FHIT to be a significant prognostic factor in patients with early breast cancer." (PMID 17164758, 2007). "In contrast, it has been demonstrated that aberrant methylation of FHIT occurred specifically in lung and breast cancers." (PMID 16928264, 2006). "‘A candidate tumour suppressor gene in this region is FHIT and some studies have shown that this gene is involved in breast cancer...’." (PMID 12771912, 2003). "Similarly FHIT gene methylation has been depicted in few solid tumors, like GIT tumors, lung and breast cancers, where it was linked to dysregulated expression." (PMID 38587694, 2024). "This means that the allelic loss in FHIT gene structure can occur in breast cancer patients regardless of patient's age, tumour grade, tumour type, and lymph node involvement." (PMID 22295218, 2011). "In breast cancer set, no significance association was observed between HD in FHIT exons and patients clinicopathological data." (PMID 22295218, 2011). "Additionally, a strong correlation was observed between exons 8 and exon 9 (P < 0.0001).We conclude that FHIT gene exons are homozygously deleted at high frequency in Egyptian women population diagnosed with breast cancer." (PMID 22295218, 2011). "A total of 62 breast cancer patients were investigated for homozygous deletion (HD) in FHIT exons." (PMID 22295218, 2011). "The same group recently reported that in MHC-I negative breast cancers the loss of NLRC5 is less frequent than the loss of FHIT, and that FHIT could be used to restore MHC-I expression." (PMID 33671123, 2021). "FHIT was co-deleted with MACROD2 in 75% of the cell lines with FHIT deletion, indicating that for certain breast cancer cell lines, replicative stress followed by DNA breakage and repair might occur during adaptation to cell culture and affect multiple common fragile site genes." (PMID 23805207, 2013). "The down-regulation of FHIT expression upon LINC00173 depletion was observed not only in A549 cells but also in non-small cell lung cancer cell line, H1299, and in breast cancer cell line, MDA-MB-231." (PMID 38069335, 2023).